INS (insulin)
Diseases named in the same sentence as INS in open-access papers (continued):
Sharing a sentence is not in itself a finding about the gene and the disease.
diabetes (continued). "Insulin is important for hepatic function and regeneration and diabetes is also a risk factor for the development of nonalcoholic fatty liver disease and cirrhosis which may lead to higher rates of PHLF." (PMID 24298201, 2013). "Thus, increased physical activity has a beneficial effect on reduction in the diabetes-associated risks by enhancing insulin sensitivity." (PMID 24454364, 2013). "Additionally, insulin detemir is associated with a unique overall weight-sparing effect in patients with diabetes." (PMID 24499517, 2013). "These benefits are likely achieved through multiple metabolic pathways: by reducing weight and waist circumference, body mass index (BMI), percent body fat and percent trunk fat mass; improving glucose metabolism and insulin sensitivity; and lowering the risk of metabolic syndrome and diabetes." (PMID 23628720, 2013). "However, in our current study, by introducing the selective TLR4 defect of the C57BL/10ScN mouse onto the NOD mouse background we were able to provide conclusive evidence for the involvement of TLR4 in the progression of insulin-deficient diabetes." (PMID 24086519, 2013). "Diabetes is associated with obesity, dyslipidaemia and hypertension, and is characterised by chronic hyperglycaemia due to insufficient insulin release, impaired insulin action, or a combination of both." (PMID 24282548, 2013). "Isotypes of insulin autoantibodies have been evaluated in the BabyDiab study and in studies from Finland with the observation that a broader response to insulin and strong IgG1 responses is associated with a somewhat greater risk of progression to diabetes." (PMID 24386337, 2013). "Diabetes is one of the classical triad of symptoms seen at advanced stages of the human iron overload disorder hemochromatosis and iron overload arising due to various causes has been associated with insulin perturbations and type 2 diabetes." (PMID 27605185, 2013). "In addition, the FTO variant is associated with diabetes-related metabolic traits (including higher fasting insulin, glucose and triglycerides, and lower HDL cholesterol), although the association disappeared after adjustment for BMI." (PMID 23977173, 2013). "Various factors are associated with glycemic control including age, sex, diabetes duration, and management (frequency of blood glucose monitoring, insulin regimen, and dose adjustments), as well as those indirectly connected to diabetes care (family history, dietary, cultural habits, etc.)." (PMID 23935617, 2013). "Several studies have been conducted to evaluate specifically expressed miRNAs in the diverse types of diabetes, particularly associated with the regulation of insulin production and secretion, differentiation of human pre-adipocytes, and association with T1D pathogenesis." (PMID 24279768, 2013). "Changes in desaturase activity are associated with insulin sensitivity and may be associated with type 2 diabetes mellitus (T2DM)." (PMID 24705214, 2013). "Using an insulin-producing RINm5F cells, a rat pancreatic islet cell type, as an experimental cell model, we present evidence here that FD is indeed a legitimate risk factor for the pathogenesis of diabetes." (PMID 24223745, 2013). "However, the insulin-sensitising effect of the PPARG 12Ala allele on skeletal muscle is either lost or masked by insulin resistance in patients with type 2 diabetes mellitus." (PMID 23799144, 2013). "Diabetes is a highly prevalent disease characterised by elevated and poorly regulated blood glucose caused by a defect in insulin production by the pancreatic beta cell, reduced insulin action in its target tissue, or a combination of the two." (PMID 23418498, 2013). "The central leptin gene therapy has also been effective to insulin-deficient diabetes in obesity animal models such as ob/ob mise, diet-induced obese mice, and insulin-deficient type 1 diabetes mice, and in patients with inactivating mutations in the leptin gene." (PMID 23579596, 2013).
diabetes (continued). "“Our society is quite ignorant of insulin therapy and they might associate insulin injection with drug addicts” (2 years of insulin use/ 5 years of having diabetes)." (PMID 24164794, 2013). "Moreover, diabetes impairs hippocampal neurogenesis in insulin-deficient rats, insulin-resistant mice, and in streptozotocin-treated diabetic rats." (PMID 24366068, 2013). "The presence of MAPK1/ELK1/CREBBP axis in the core subnetwork and its direct crosstalk to the insulin pathway is consistent with experimental observations that link insulin signaling and diabetes risk to the regulation of learning and formation of long-term memory." (PMID 23885764, 2013). "The results of this study revealed that lower HbA1c levels and a shorter duration of diabetes at insulin initiation were associated with better glycemic control and withdrawal due to HbA1c improvement; hence, earlier intervention is important for successful glycemic control in patients with T2DM." (PMID 24011395, 2013). "Regular physical activity may improve glycaemic control, insulin sensitivity, and cardiovascular risk factors (e.g., blood pressure, lipid profile, and body composition) in people with diabetes." (PMID 23738538, 2013). "If Sertoli cell function is causally linked to insulin resistance, then changes in Sertoli cell output may contribute to age-related increase in the incidence of Type 2 diabetes mellitus and related complications." (PMID 23940675, 2013). "This atrophy of the testes is mainly due to the decrease in testosterone level associated with the absence or diminution of serum insulin levels, since insulin acts as an anti-apoptotic factor capable to regulate testicular apoptosis and sexual dysfunction induced by diabetes." (PMID 23548080, 2013). "This was an intuitively appealing hypothesis given the enhanced damage caused by ischemia in patients with uncontrolled diabetes who lack insulin and are thereby hyperglycemic." (PMID 24223835, 2013). "Diabetes mellitus (DM) is a series of endocrine metabolic disorders characterized by increased fasting and postprandial glucose levels as well as an insulin deficiency and/or defects of insulin action on regulation of glucose." (PMID 24167738, 2013). "The respective contribution of the different diabetes-associated stresses to dysfunction and death of insulin-secreting cells remains unclear." (PMID 24349266, 2013). "Increased susceptibility to CVD and diabetes may be due, in part, to high free-radical level in plasma which impairs insulin function." (PMID 31667003, 2013). "In contrast, lower AIRG and DI represent an inability of the pancreas to secrete enough insulin at a given level of insulin resistance where impaired glucose tolerance may arise (i.e., higher diabetes risk)." (PMID 23762538, 2013). "South Asians are known to be more insulin resistant than other ethnic groups and it is hypothesised that the high prevalence of diabetes in SA communities is due to their increased susceptibility to developing insulin resistance." (PMID 22828963, 2013). "Known associations between diabetes and cancer could logically be attributed to hyperglycemia, hypersecretion of insulin, and/or insulin resistance." (PMID 23405181, 2013). "Moreover, conditional knockout of GLIS3 in adult mice causes defective insulin secretion and increase susceptibility to high fat diet-induced diabetes." (PMID 23737756, 2013). "Diabetes is caused by absolute insulin deficiency due to autoimmune destruction of insulin-secreting pancreatic β-cells (type 1 diabetes) or by relative insulin deficiency due to decreased insulin sensitivity, usually observed in overweight individuals (type 2 diabetes)." (PMID 23554816, 2013).
diabetes (continued). "In subjects with diabetes (n = 282), 25(OH)D levels were negatively associated with waist circumference, fasting insulin, HOMA-IR, triglyceride levels, and visceral abdominal fat, and were positively associated with LAI after adjusting for age, sex, season, exercise, and vitamin supplementation." (PMID 24130687, 2013). "Insulin resistance (IR), that is, reduced responsiveness to insulin in liver, muscle, and adipose tissue, is closely associated with various metabolic diseases such as obesity, metabolic syndrome, nonalcoholic fatty liver disease, and type 2 diabetes mellitus." (PMID 24204385, 2013). "Deficiency of this machinery leads to insufficient insulin that may contribute to the pathogenesis of diabetes." (PMID 23630453, 2013). "Additionally, it has been demonstrated that some of these polymorphisms are associated with type 2 diabetes mellitus, insulin secretion, as well as with metabolic changes related to obesity." (PMID 23855914, 2013). "We observed impairments in two factors (insulin sensitivity and glucose effectiveness), indicating that post-term children may be at increased risk of later type 2 diabetes mellitus." (PMID 23840881, 2013). "Diabetes is an important chronic health problem associated with insulin resistance, increased insulin level, changes in growth hormones and factors, and activation of mitogen-activating protein kinase (MAPK) pathways, leading to an increased breast cancer risk." (PMID 23401790, 2013). "Cognitive dysfunction and impaired synaptic plasticity in both types of diabetes have been linked to hyperglycemia, insulin deficiency and/or insulin resistance and altered insulin signaling, hypophyseal-pituitary axis hyperactivity and elevated glucocorticoid levels." (PMID 24555069, 2013). "Following these observations, we used a logistic regression analysis to evaluate whether these SNPs were independently associated with DR after adjusting for duration of diabetes, insulin therapy, BMI, HbA1c, total LDL, HDL, and cholesterol levels." (PMID 24228244, 2013). "Raised nonesterified fatty acid concentrations in plasma have been proposed as a major cause of insulin resistance and may reduce the secretion of insulin in diabetes." (PMID 24250639, 2013). "Indeed, unsuppressed hyperglucagonaemia plays a major role in hyperglycaemia in all forms of insulin-deficient diabetes." (PMID 23132340, 2013). "Inclusion of the PDX1 gene in mutation screening for permanent neonatal diabetes is recommended as a genetic diagnosis reveals the mode of inheritance, allows accurate estimation of recurrence risks and confirms the requirement for insulin treatment." (PMID 23320570, 2013). "Disrupted neuronal insulin action may underlie the link between diabetes and neurodegenerative disorders." (PMID 23896654, 2013). "This rarefaction of the retinal microcirculation in South Asians is more prominent in the smaller (higher order) arterioles and is unexplained by blood pressure, diabetes, insulin resistance, or other cardiovascular risk factors known to influence the retinal microvascular architecture." (PMID 24116136, 2013). "In diabetes, deficient function of insulin-dependent lipoprotein lipase may lead not only to hypertriglyceridemia but also to decreased HDL-cholesterol levels." (PMID 23398881, 2013). "Diabetes is caused by absolute or relatively insufficient insulin secretion." (PMID 23421382, 2013). "Type 2 diabetes mellitus is a polygenic disorder that is caused by a metabolic and/or hormonal imbalance between insulin secretion from β cells and insulin sensitivity in peripheral tissues, both of which might be modified by genetic and environmental factors." (PMID 23691524, 2013). "Some common myths in South Asia include the use of calorie-rich foods for regaining health, avoiding the use of insulin injections to prevent diseases, and the idea that diabetes may be caused by supernatural entities." (PMID 23497693, 2012).
diabetes (continued). "In patients with long standing diabetes, the metabolic consequences of insulin resistance are mediated predominantly by abnormalities along the metabolic pathway of insulin signalling caused primarily by exogenous insulin administration." (PMID 22870170, 2012). "Resistance to the actions of insulin is strongly associated with renal complications of diabetes." (PMID 22448165, 2012). "A consensus article by the American Diabetes Association and the European Association for the Study of Diabetes states that the expected decrease of HbA1c levels with Metformin and Thiazolidinedione monotherapy is 1%-2%, and with Insulin a decrease of 1.5%–3.5% can be expected." (PMID 23304164, 2012). "Although this pathway is less understood, if certain types of phthalates dysregulate glucose metabolism by impacting lipid handling, then these phthalates could impact diabetes risk by altering beta-cell insulin secretion." (PMID 22796563, 2012). "Thus, chemically induced diabetes in animals has been widely used as an experimental model for studying complications caused by diabetes and the effects of physical exercise on insulin resistance and fat metabolism." (PMID 23067133, 2012). "Generally, diabetes is classified into two main types: type-1 diabetes, a state of insulin deficiency because of defect in islet β-cell function and type-2 diabetes which mainly characterized by resistance to the actions of insulin." (PMID 23304131, 2012). "Elevated levels of valine and leucine, and decreased concentrations of glycine in PCOS plasma could contribute to insulin sensitivity and could be considered as the potential biomarkers for long-term risk assessment of diabetes mellitus." (PMID 23198915, 2012). "The results also suggest that translational mechanisms through phosphorylation of eukaryotic initiation factor-2α (eIF2α) may underlie the upregulation of BACE1 associated with insulin-deficient diabetes." (PMID 22403710, 2012). "A previous study showed that alloxan-induced diabetes is associated with changes in the uptake of insulin by the brain, which includes increased binding to the capillary bed comprising the blood brain barrier and increased transport across the blood brain barrier." (PMID 22645603, 2012). "Because many of these problems may be reduced by improved glycemic control, efforts to maintain nearly normal levels of glucose are recommended during pregnancy associated with diabetes, frequently requiring the use of insulin." (PMID 22685467, 2012). "Furthermore, the STZ-induced diabetes model is insulin deficient and likely to exhibit a reduced ability to efficiently use glucose as an energy source." (PMID 22347376, 2012). "First, we used HbA1c instead of fasting glucose and insulin to evaluate diabetes risk." (PMID 23006958, 2012). "Fasting plasma glucose, insulin levels, body mass index (BMI), and waist circumference are measured at baseline and 12 months, as are patients' self-reported behavioral and emotional responses to diabetes risk information." (PMID 22257365, 2012). "In this study, we investigated the effects of clevudine exposure on mtDNA content, mitochondrial function, and metabolism-secretion coupling in insulin-releasing cells to elucidate the mechanism underlying the reversible diabetes observed in clevudine-treated patients." (PMID 22230186, 2012). "Diabetes mellitus (DM), a metabolic disorder characterized by hyperglycemia, is caused by insufficient insulin production due to excessive loss of pancreatic β cells (type I diabetes) or impaired insulin signaling due to peripheral insulin resistance (type II diabetes)." (PMID 22506114, 2012). "The American Diabetes Association and the American Association of Clinical Endocrinologists, based on the available evidence, set an upper limit at 180 mg/dL (10 mmol/L), at which insulin therapy should be started." (PMID 22400022, 2012).
diabetes (continued). "However, this flexibility cannot restore normal insulin secretion processes linked to glucose sensing, thereby inducing a pathogenic pathway leading to diabetes." (PMID 23300881, 2012). "GI may be a relatively less important risk factor in patients with diabetes where hyperglycemia is primarily due to peripheral insulin resistance (and deficient insulin secretion)." (PMID 22927948, 2012). "Additionally, there were phenotypes associated with diseases of energy metabolism such as diabetes, these phenotypes included insulin resistance, abnormal glucose homeostasis and increased circulating insulin level." (PMID 22257742, 2012). "In addition, amino acids have been identified as predictors of the risk of developing diabetes and possibly contributing to changes in insulin sensitivity." (PMID 22808006, 2012). "It should also be acknowledged that, although our study shows a clear association between insulin sensitivity deterioration and diabetes onset, whether this is a causal relationship cannot be concluded with certainty." (PMID 23185618, 2012). "Indeed, mitochondrial dysfunction causes deposits of lipids inside the muscle, producing insulin resistance and leading to diabetes." (PMID 22523671, 2012). "Insulin is the main hormone regulating glucose metabolism, and improved insulin sensitivity could reduce the risk of diabetes." (PMID 22407339, 2012). "Type 1 diabetes mellitus (T1DM) is an autoimmune disease that immune self-reactive T cells damage the insulin producing pancreatic β-cell and cause insulin deficiency, hyperglycemia and long-term medical complications such as neuropathy, retinopathy and kidney failures." (PMID 23843817, 2012). "The presence of a variable-number tandem repeat (VNTR) in the 5′ region of the INS promoter suggests that INS is potentially an imprinted gene, and its imprinting status could be associated with insulin-dependent diabetes mellitus." (PMID 22393450, 2012). "There is a possibility of selection bias since the study population was limited and recruited from a patient association offering different activities such as diabetes education, giving patients an enabling environment to share disease experiences and access to low-cost insulin." (PMID 23396799, 2012). "As a result, high glucose levels in the blood stimulate insulin secretion and in the long run may cause IR and diabetes." (PMID 23031426, 2012). "In addition to KEGG analysis, LSI analysis revealed that the significantly altered proteins were highly associated with the input interrogation terms ‘diabetes’ and ‘insulin’." (PMID 23094041, 2012). "However, HF feeding alone is insufficient to cause diabetes due to the capacity of pancreatic β-cells to increase insulin secretion in order to compensate for the insulin resistance." (PMID 22860063, 2012). "Diabetes mellitus, a disease affecting a quarter of a billion people worldwide, can cause skeletal muscle damage and atrophy via diabetic neuropathy and by the more direct effects of high glucose and low insulin on muscle cell metabolism." (PMID 23239980, 2012). "An individual with diabetes, achieving moderate weight loss with physical activity may control their blood sugar and improve insulin sensitivity." (PMID 23121755, 2012). "Biological factors – for instance, higher insulin levels due to untreated disease - and others underlying the association between previously diagnosed diabetes and breast cancer could differ in those whose diabetes remains undiagnosed until cancer." (PMID 23259613, 2012). "Although evidence is accumulating that diabetes mellitus is an important risk factor for sporadic Alzheimer's disease (AD), the mechanisms by which defects in insulin signaling may lead to the acceleration of AD progression remain unclear." (PMID 22403710, 2012).